TRIOBP (TRIO and F-actin binding protein)
Diseases named in the same sentence as TRIOBP in open-access papers (continued):
Sharing a sentence is not in itself a finding about the gene and the disease.
idiopathic pulmonary fibrosis (1 paper, 2023). Idiopathic pulmonary fibrosis (IPF) is a nonneoplastic pulmonary disease that is characterized by the formation of scar tissue within the lungs in the absence of any known cause. "Recently, our study identified that F-Actin Binding Protein (TRIOBP) is one of the target genes of miR-29b and found that deficiency of TRIOBP increases resistance to lung fibrosis in vivo." (PMID 38157020, 2023). "Transcription factor β-catenin is involved in alveolar epithelial–mesenchymal transition during pulmonary fibrosis, we hypnotized that TRIOBP interacts with TRIO modulating fibrosis through β-catenin signal pathway." (PMID 38157020, 2023). "Our findings exhibit that TRIOBP is one of the target genes and discovers a novel mechanism that miR-29b blocks pulmonary fibrosis by regulation of TRIOBP and TRIO." (PMID 38157020, 2023). "In conclusion, the present work revealed the role and mechanism of the miR-29b–TRIOBP–TRIO–β-catenin axis in lung fibrosis and provided a better understanding for IPF." (PMID 38157020, 2023). "To evaluate the potential role of TRIOBP in lung injury and fibrosis in vivo, we generated the mice model of lung fibrosis and shRNA adenovirus targeting Triobp treatment mice model." (PMID 38157020, 2023). "Next, we explored the molecular mechanism of TRIOBP in pulmonary fibrosis." (PMID 38157020, 2023). "The results from in vitro and in vivo experiments indicated that increasing with miR-29b or interfering with TRIOBP expression may be effective strategies for the prevention and treatment of lung fibrosis." (PMID 38157020, 2023). "The miR-29b–TRIOBP–TRIO–β-catenin axis might be a key anti-fibrotic axis and provide a promising treatment strategy for lung fibrosis." (PMID 38157020, 2023). "We concluded that the miR-29b‒TRIOBP–TRIO–β-catenin axis might be a key anti-fibrotic axis in IPF to regulate lung regeneration and fibrosis, which may provide a promising treatment strategy for lung fibrosis." (PMID 38157020, 2023).
neuroblastoma (1 paper, 2014). Neuroblastoma (NB) is the most common solid, extracranial childhood tumor. "It was confirmed that antibody 6H11 was able to recognise recombinant human TRIOBP-1 fused to Maltose Binding Protein (MBP), but not MBP alone and also detected the same major 70 kDa band as a polyclonal antibody against TRIOBP in neuroblastoma cells." (PMID 25333879, 2014).
pancreatic cancer (1 paper, 2018). "The same trend of expression was revealed for TRIOBP, already described in pancreatic cancer where is involved in cell motility and migration through cytoskeleton remodeling." (PMID 29871612, 2018).
cancer (7 papers, 2015 to 2024). A tumor composed of atypical neoplastic, often pleomorphic cells that invade other tissues. "In contrast to the general expression of TRIOBP-1 and, to a lesser extent, longer TRIOBP splice variants in cancer, TRIOBP-4 transcripts were specifically seen to be expressed in a cancer cell line, HPAC." (PMID 33121024, 2020). "TRIOBP variant 1 and TRIOBP variant 4 have been reported to have completely different functions, but both have been found to be associated with cancer." (PMID 29890989, 2018). "In this review, the categories of three major TRIOBP variants for human diseases and subcellular functions are discussed as well as recent associations between TRIOBP and cancer." (PMID 29890989, 2018). "Finally, a new anti-cancer strategy would be identified through a study of the cancer mechanism of TRIOBP variants." (PMID 29890989, 2018). "However, recent studies provide clues that TRIOBP variants are associated with other human diseases including cancer and brain diseases." (PMID 29890989, 2018). "However, recent studies have shown that all TRIOBP variants may contribute to most cancers including GBM." (PMID 29890989, 2018). "The Cancer Genome Atlas (TCGA) analysis also confirms that TRIOBP mRNA is enhanced in most cancer patients." (PMID 29890989, 2018). "In the blue module (associated with the untreated cancer cells), the enriched pathways were “Cilium Disassembly”, “Microtubule”, “Tubulin Binding”, “Myosin Binding”, and “Lamellipodium Assembly”, where the genes KIF1C, MAP4, ACTG1, ABLIM3, TRIOBP are involved." (PMID 38534323, 2024). "An area where the TRIOBP isoforms show greater overlap is in the pathology of cancer." (PMID 33121024, 2020). "Although the mutation could not be determined as contributing to cancer, TRIOBP may be a hereditary factor in cancer." (PMID 29890989, 2018). "In addition, understanding TRIOBP function during the cell cycle such as mitosis or interphase could provide anti-cancer strategies for tumorigenesis." (PMID 29890989, 2018).
mental illness (4 papers, 2020 to 2022). "The TRIOBP locus therefore encodes a variety of distinct proteins with TRIOBP-1 being a structured and ubiquitously expressed protein implicated in mental illness and TRIOBP-4 being a disordered protein with specialized expression pattern essential for hearing." (PMID 33121024, 2020). "Determining mechanistic details of the two paths by which TRIOBP can form protein aggregates, therefore, represents an important next step in investigating this emerging aspect of mental illness molecular pathology." (PMID 36232351, 2022). "In contrast to findings with the high stringency protocol, the abundance of these TRIOBP species is actually decreased in mental illness." (PMID 36232351, 2022). "It is therefore possible that aggregation of longer TRIOBP isoforms may also play a role in mental illness pathogenesis." (PMID 36430976, 2022). "It is therefore possible that aggregation of longer TRIOBP isoforms may play a role in mental illness, but this remains to be investigated." (PMID 33121024, 2020). "In order to confirm whether aggregated TRIOBP is present in the brains of patients with major mental illness, we optimized two previously published protocols for isolating the insoluble protein fraction of brain tissue which will be referred to as the high and low stringency purification techniques." (PMID 36232351, 2022). "The second part of the review addresses the known proteins whose aggregation in brain tissue has been observed in psychiatric disorders (amyloid, tau protein, α-synuclein, DISC-1, disbindin-1, CRMP1, SNAP25, TRIOBP, NPAS3, GluA1, FABP, and ankyrin-G)." (PMID 36430976, 2022).
TRIOBP also shares sentences with these, for which no sentence is quoted: autosomal recessive deafness (5 papers); Hearing impairment (5); depression (3); breast carcinoma (2); melanoma (2); age (1); brain diseases (1); deafness autosomal dominant 10 (1); epilepsy (1); hearing (1); hearing disorder (1); lung carcinoma (1); male infertility (1); pituitary adenomas (1); squamous cell carcinoma (1); thymoma (1); tumor (1); Vertigo (1).